CRP (C-reactive protein)
Diseases named in the same sentence as CRP in open-access papers (continued):
Sharing a sentence is not in itself a finding about the gene and the disease.
diabetes (continued). "Stone size, stone number, history of UTI, positive urine culture, positive urine nitrite, CRP levels, operation time, stent placement, and diabetes mellitus were significantly associated with urosepsis following URSL (P < 0.05)." (PMID 40611921, 2025). "Then, we investigated the moderation effect of CRP on the associations between vitamin D deficiency (<10 ng/mL) and incident diabetes and performed subgroup analyses according to age (<60 vs. ≥60 years) and frailty status (frail; pre-frail; non-frail)." (PMID 39662157, 2025). "The result showed that men with CRP levels in the highest quartile (CRP ≥2.91 mg/L) exhibited a 2.7 times higher risk of developing diabetes." (PMID 39355932, 2025). "Logistic regression analysis showed that diabetes and hs‐CRP were risk factors for ISR after PCI (OR > 1, p < 0.05)." (PMID 40056066, 2025). "Logistic regression analysis identified several independent risk factors for poor treatment outcomes, including diabetes, cavities in the lungs, tracheobronchial TB, increased C-reactive protein, and decreased hemoglobin." (PMID 40206468, 2025). "Multivariable logistic regression examined associations of catheter-associated UTI (CAUTI), time-to-effective therapy, baseline CRP, diabetes, early catheter removal/exchange (≤48 h), and early intravenous-to-oral switch (≤72 h) with non-response." (PMID 41462885, 2025). "Our analyses also demonstrated significant interactions between levels of CRP and vitamin D deficiency in incident diabetes." (PMID 39662157, 2025). "Elevated CRP levels have been associated with increased risks of metabolic syndrome, cardiovascular disease, coronary heart disease, myocardial infarction, diabetes, and colon cancer." (PMID 41292546, 2025). "Logistic regression incorporating all biomarkers yielded a modest predictive accuracy of 33.3%, with CRP emerging as the most influential predictor of diabetes risk, followed by IL-6." (PMID 41523554, 2025). "Patient factors, such as diabetes mellitus, hypoalbuminemia, elevated preoperative C-reactive protein (CRP) levels, and immunosuppressive therapy are associated with increased infection risks." (PMID 41253895, 2025). "Fiber intake is associated with lower levels of the inflammatory serum marker C-reactive protein (CRP) and improved insulin sensitivity, which in turn can mitigate the chronic inflammatory state associated with diabetes and depression." (PMID 40658313, 2025). "No significant mediating effects were observed for higher hs-CRP levels, vitamin D deficiency, obesity, central obesity, diabetes mellitus, and hypertension." (PMID 40614606, 2025). "Methylation risk score of C-reactive protein is a strong marker of systemic inflammation, showing stronger associations with poor sleep traits and related conditions like diabetes and hypertension in a diverse Hispanic/Latino cohort." (PMID 40437222, 2025). "In general, older age, longer diabetes duration, and worse glycemic indices are known risk factors for DR, and they also tend to be associated with higher CRP." (PMID 41159344, 2025). "The analysis revealed that stone size, stone number, history of UTI, positive urine culture, positive urinary nitrites, elevated CRP levels, prolonged operative time, stent placement, and diabetes mellitus were significantly associated with postoperative US." (PMID 40611921, 2025). "Carotid VC, diabetes, low serum albumin, high serum C-reactive protein (CRP), and the presence of cardiovascular diseases are associated with all-cause and cardiovascular mortality." (PMID 40136613, 2025). "In our cohort, only CRP/Alb showed a significant association with diabetes, possibly due to population differences or the limited number of diabetic participants." (PMID 41302334, 2025). "Elevated CRP levels are associated with metabolic disease, including dyslipidemia, diabetes, and metabolic syndrome, and are used to assess the risk of cardiovascular diseases at large." (PMID 40630018, 2025).
diabetes (continued). "Polygenic risk score analysis for traits relevant to diabetes found that C-reactive protein showed a positive association, whereas PRS for fasting insulin showed a negative association with neuropathic pain, in individuals with diabetic polyneuropathy." (PMID 39471050, 2025). "Nonetheless, in multivariate logistic regression analysis of the ACS group, age, male sex, diabetes, smoking, DL, CRP, and PCT levels were significantly associated with disease presence." (PMID 40963340, 2025). "Similar associations between vitamin D or CRP and incident diabetes were found in younger and older adults and in normal and frail or pre-frail older adults." (PMID 39662157, 2025). "The meta-analysis results highlight advanced age, prolonged dialysis duration, concomitant diabetes, hypertension, hyperparathyroidism, and elevated levels of CRP, hs-CRP, and SOST as key risk factors for CAC in ESRD patients." (PMID 40314886, 2025). "Type 2 diabetes mellitus is strongly associated with elevated levels of IL-6, leptin, CRP, and TNF-α." (PMID 41155523, 2025). "Our findings showed that increased preoperative CRP levels and diabetes were associated with PJI following RSA surgery." (PMID 40363957, 2025). "Among those risk factors, age ≥65 years, diabetes, male sex, and CRP elevation are associated with hospitalisation in both, patients with cystitis and PN." (PMID 40262850, 2025). "Mono-isobutyl phthalate (MiBP), a metabolite of DiBP, is not only associated with the occurrence of diabetes and hyperuricemia but also with elevated C-reactive protein (CRP) levels, a marker of systemic inflammation." (PMID 40352847, 2025). "Our research illustrates that individuals with CRP >2 mg/L were more likely to present with comorbid risk factors for AF such as obesity, hypertension, diabetes mellitus, and HF." (PMID 41387931, 2025). "Data on risk factors (age, gender, diabetes, BMI, smoking) and laboratory results (CRP, WBC, blood cultures) were collected." (PMID 41255490, 2025). "The significant reduction in CRP levels associated with propolis supplementation suggests its promise as a novel adjunctive strategy for the prevention and management of both diabetes and cardiovascular disease." (PMID 41141253, 2025). "NF-κB-mediated signaling plays a pivotal role in diabetes-associated neuro-inflammation, and our observed decrease in CRP is directionally consistent with melatonin's immune-regulatory effects." (PMID 41281014, 2025). "Using data from the UK Biobank cohort, we showed inverse and positive associations of vitamin D and CRP levels with incident diabetes in ambulatory community-dwelling middle-aged and older adults." (PMID 39662157, 2025). "Participants with periodontitis or diabetes had a greater proportion in the highest hs-CRP quartile and high-risk ADA/CDC category compared to those without these conditions." (PMID 41153725, 2025). "Our findings add clinical value by showing that exercise reduces these markers even in high-risk subgroups: for example, older adults with diabetes had a significant CRP reduction, a change associated lower CVD risk in this population." (PMID 41561801, 2025). "This study enrolls high-risk patients without a history of ASCVD, provided they have an Lp(a) level of ≥175 nmol/L and have 3 risk enhancers such as elevated CAC score, elevated hs-CRP, or diabetes." (PMID 40932828, 2025). "This study aims to analyze the heterogeneity of mortality risk in patients with comorbid diabetes mellitus (DM) and HF using the C-reactive protein-triglyceride-glucose index (CTI)." (PMID 41347140, 2025). "Lower vitamin D and higher CRP levels were significantly associated with an increased risk of diabetes during follow-up." (PMID 39662157, 2025). "The results showed that diabetes and hs‐CRP were risk factors, and SFRP5, ApoA‐I, and HDL3‐C were protective factors for ISR after PCI (OR < 1, p < 0.05)." (PMID 40056066, 2025).
diabetes (continued). "Poorly controlled diabetes (HbA1c ≥ 7%) was associated with higher levels of inflammatory markers such as CRP, IL-6, and ferritin, as well as elevated composite indices (NLR, SII)." (PMID 40299484, 2025). "MRS-CRP is the only CRP measure to have strong associations (q-value < 0.001) with both diabetes (OR = 2.44, [2.06, 2.90]) and hypertension (OR = 1.29, [1.10, 1.50])." (PMID 40437222, 2025). "In participants with higher levels of CRP, the hazard ratio of developing diabetes comparing participants who had vitamin D deficiency to those who did not was lower than that in participants with lower levels of CRP." (PMID 39662157, 2025). "In clinical settings, the use of salivary CRP has demonstrated positive correlations with serum CRP levels, showcasing its potential as a diagnostic tool for conditions such as diabetes." (PMID 38741881, 2024). "A number of studies demonstrated that high levels of hs-CRP and IL-6 are associated with high blood pressure, independently of diabetes." (PMID 39404426, 2024). "Elevated CRP levels have been linked to chronic systemic diseases, such as type 2 diabetes, contributing to endothelial dysfunction and vascular remodeling in diabetes." (PMID 38281018, 2024). "In the sensitivity analysis, repeated measurements of CRP, as an inflammatory marker, were collected to further explore the association between diabetes control and inflammation risk." (PMID 39720249, 2024). "Results of the retrospective multicenter study found that age, diabetes, heart failure, higher CRP, and lower BMI all impact the risk of adverse outcomes (mortality and complications within 30 days) of PEG patients." (PMID 38337398, 2024). "This suggested that if LDL cholesterol, HOMA for insulin resistance, or C-reactive protein mediated the association between triglycerides and diabetes in subsequent analyses, the mediation would be partial rather than complete." (PMID 38611646, 2024). "Significant direct association with TIMP-1 was found for age (p < 0.001), smoking (p = 0.042), CRP (p < 0.001), BMI (p < 0.001), hypertension (p < 0.001), and diabetes (p < 0.001), and inverse association with female gender (p < 0.001)." (PMID 39917664, 2024). "Increased CRP is associated with aging, obesity, diabetes, high blood pressure, and insulin resistance." (PMID 39684992, 2024). "Imbalanced diabetes is attributed to high CRP levels resulting from systemic inflammation caused by AGEs." (PMID 39595081, 2024). "We also found a statistically significant association between high CRP levels and the presence of diabetes (p-value = 0.0149), hypertension (p-value = 0.0243), and dyslipidemia (p-value = 0.0423)." (PMID 38983990, 2024). "CRP is positively associated with an increased risk of insulin resistance and diabetes in both adolescents and adults." (PMID 39339686, 2024). "Depression showed a negative association with income-to-poverty ratio, vigorous recreational activities, CVD, stroke, hypertension, diabetes, BMI, waist, and CRP, and smoking status was found to be positively associated with depression." (PMID 38684752, 2024). "Higher levels of WBCs and their subtypes (neutrophils, monocytes, lymphocytes, and eosinophils), platelet count, and inflammatory markers like CRP (C-reactive protein) are associated with an increased risk of cardiovascular diseases and diabetes 20–22." (PMID 38212326, 2024). "There is a strong association between the CRP rs1800947 and CRP expression and it has been shown to be associated with heart disease, diabetes, and cancer." (PMID 38184750, 2024). "Detection of CRP can help in monitoring the body's inflammatory state and response to treatment or lifestyle changes in individuals with diabetes to reduce the risk of serious complications such as heart disease and stroke." (PMID 39091901, 2024). "Higher CRP levels are associated with tissue damage, infection, atherosclerosis, arterial hypertension, obesity, diabetes, and/or cancers." (PMID 38172843, 2024).
diabetes (continued). "Data shows statistically significant associations between elevated C-reactive protein levels and the presence of arterial hypertension,diabetes mellitus and smoke/tobacco use." (PMID 40092874, 2024). "In the Women’s Health Study, there was an increased risk of developing diabetes for those in the highest vs. lowest quartile of baseline IL-6 (RR: 2.3 [0.9, 5.6]) and CRP (RR: 4.2 [1.5 – 12.0])." (PMID 38665261, 2024). "The relationship between systemic inflammation and CRP is complex, with C-reactive protein levels correlating with the risk of cardiovascular disease, diabetes, metabolic syndrome, rheumatoid arthritis, lung disease, and depression." (PMID 39720727, 2024). "Metabolically vulnerablesubgroups, such as the elderly, participantswith diabetes or prediabetes, high BMI, or elevated hs-CRP levels,appear to exhibit an increased susceptibility to the detrimental effectsof air pollution exposure." (PMID 39365792, 2024). "These individuals also reported higher energy intake, more frequent engagement in recreational activities, and exhibited lower risks of hypertension, diabetes, depression, and all-cause mortality, alongside reduced C-reactive protein levels." (PMID 38684752, 2024). "For TIMP-1, significant positive associations were found with smoking, CRP and obesity, and an inverse association with prevalent diabetes." (PMID 39917664, 2024). "C-reactive protein (CRP) is an important inflammatory marker that elevates in T1D, increases the risk of all-cause mortality in diabetes, and predicts cardiovascular events in asymptomatic populations and those with poorly controlled diabetes." (PMID 38999806, 2024). "CRP levels increase during infections and in chronic inflammatory disease linked to cardiovascular disease, cancer, and diabetes." (PMID 38571307, 2024). "Diabetes mellitus has been previously reported as a systemically proinflammatory state, and elevated CRP in the first trimester has been significantly associated with developing gestational diabetes." (PMID 38267943, 2024). "Female sex, older age, lower kidney function, albuminuria, diabetes, hypertension, and recent anaemia were associated with higher odds of C-reactive protein ≥ 2 mg/L." (PMID 39211962, 2024). "Logistic regression analysis revealed that a high SII, advanced age, diabetes, total albumin, and CRP concentration > 20.25 mg/L were independent risk factors for POD in older patients with intertrochanteric fractures." (PMID 38566241, 2024). "Child abuse history predicted C-reactive protein and increased the risk of gestation diabetes mellitus (GDM)." (PMID 38787894, 2024). "Some studies also suggest a strong association between WBC, hs‐CRP, and metabolic syndrome, diabetes, and cardiovascular health." (PMID 39364712, 2024). "The findings indicated that diabetes, dyslipidemia, smoking, hypertension, and elevated C-reactive protein levels are significant risk factors for plaque neovascularization." (PMID 39253361, 2024). "The obtained results of studies in the scope of CRP concentration confirm the results of previous reports that obesity and diabetes cause inflammation." (PMID 38250713, 2024). "Three independent risk factors for hypoactive delirium were identified: diabetes mellitus (OR 3.305, 95% CI: 1.866–12.616; p = 0.047), CRP level (OR 1.002, 95% CI: 1.001–1.023; p = 0.044), and IL-6 level (OR 1.045, 95% CI: 1.017–1.063; p = 0.001)." (PMID 38523173, 2024). "It was identified as an independent andcumulative risk marker of coronary heart disease, together with diabetes,hypertension, hypercholesterolemia, and elevated C-reactive protein (CRP)." (PMID 39355605, 2024). "While age, diabetes mellitus, smoking, systolic blood pressure, and serum C-reactive protein concentration were positively associated with CI, intradialytic weight gain, body mass index, and serum albumin level were negatively associated." (PMID 38225279, 2024).
diabetes (continued). "Studies identified age, C-reactive protein levels, CA 19-9, diabetes mellitus, and active smoking as independent risk factors for early mortality." (PMID 38249287, 2023). "The results showed that the duration of diabetes, HbA1c, eGFR, TcPO2, CRP, and low serum 25(OH)VD level was independent risk factors for DFU." (PMID 36829206, 2023). "After adjustment for age, sex, race, BMI, diabetes mellitus, time from symptom onset to transfusion, vaccination status, C-reactive protein, and variant wave, the SDHR remained the same (P = .62)." (PMID 36722044, 2023). "For example, there is growing evidence that markers of inflammation and oxidative stress, such as C-reactive protein (CRP), are associated with the increased risk of diseases, including diabetes, cardiovascular disease (CVD), cancer, and dementia." (PMID 37513566, 2023). "Diabetes is associated with chronic inflammation, which is mainly due to increased plasma concentrations of C-reactive protein (CRP), fibrinogen, interleukin-6 (IL-6), interleukin-1 (IL-1), and TNF α." (PMID 37974282, 2023). "A controlled trial investigating the impact of liraglutide, in combination with metformin, on patients with CAD and recent diagnostic type 2 diabetes mellitus demonstrated a reduction in CRP levels." (PMID 37760885, 2023). "High-sensitivity C-reactive protein (hs-CRP) is one of the well-recognized markers for inflammation and has been associated with many complications and chronic diseases among patients with diabetes." (PMID 37496018, 2023). "No findings from similar population-based studies conducted in the Scandinavian countries investigating the association between CRP and incident diabetes have been previously reported." (PMID 37775289, 2023). "The present study aimed to evaluate PAB and its association with high‐sensitivity C‐reactive protein (hs‐CRP) in the serum of postmenopausal women with diabetes mellitus." (PMID 36577716, 2023). "It is associated with several other established cardiovascular risk factors, such as C-reactive protein, hypertension, diabetes, and renal function, which limits the value of PCT as an independent cardiovascular risk predictor." (PMID 36835296, 2023). "Although the strength of the association reduced in the fully adjusted model, positive association remained and the participants in hs-CRP tertile 3 had 73% higher odds of future diabetes (OR 1.73; p=0.004; 95% CI 1.20 to 2.49)." (PMID 37775289, 2023). "The significance of CRP as a diagnostic tool is enhanced by understanding its association with the development of diabetes, cardiovascular disease (CVD), and autoimmune diseases." (PMID 39554800, 2023). "Sleep is also strongly associated with C-reactive protein (CRP), a protein involved in the body’s response to inflammation, which predicts cardiovascular events and diabetes." (PMID 38136035, 2023). "Fish oil supplementation was significantly associated with lower CRP levels after full adjustment for potential risk factors (p < 0.001 for prediabetes and p = 0.009 for diabetes)." (PMID 37513593, 2023). "Patients with coronary artery disease (CAD) combined with diabetes have a higher risk of cardiovascular events, and high-sensitivity C-reactive protein (hs-CRP)-to-albumin ratio (CAR) is a novel inflammatory biomarker." (PMID 36747210, 2023). "Associations with age of diabetes onset, HbA1c, hs-CRP and lipid values were evaluated in multivariate regression models." (PMID 37732126, 2023). "In a cohort study conducted among the Rotterdam population, daily consumption of 50 g of processed meat was associated with a 0.12 mg/L increase in C-reactive protein level and an elevated risk of diabetes." (PMID 38201937, 2023). "Later data demonstrated that recurrent ischemic stroke (RIS) is associated with advanced age, male sex, diabetes, H-type hypertension, and C-reactive protein." (PMID 37051146, 2023).